ATP6V1H (ATPase H+ transporting V1 subunit H)
Description:
Subunit of the V1 complex of vacuolar(H+)-ATPase (V-ATPase), a multisubunit enzyme composed of a peripheral complex (V1) that hydrolyzes ATP and a membrane integral complex (V0) that translocates protons. V-ATPase is responsible for acidifying and maintaining the pH of intracellular compartments and in some cell types, is targeted to the plasma membrane, where it promotes acidification of the extracellular environment (By similarity). The V-ATPase complex also acts as an activator for mTORC1 on lysosomal membrane by promoting the guanine nucleotide exchange factor (GEF) of the Ragulator complex, thereby enabling mTORC1 recruitment. Subunit H is essential for V-ATPase activity, but not for the assembly of the complex (By similarity). Involved in the endocytosis mediated by clathrin-coated pits, required for the formation of endosomes.
Synonyms: NBP1; CGI-11; SFD; VMA13; SFDalpha; SFDbeta; MSTP042
Tractability: Small molecule: a structure with a bound ligand is known. Antibody: UniProt places it where antibodies can reach, with high confidence; its Gene Ontology location is reachable by antibodies, with high confidence. PROTAC: ubiquitination databases record sites on it; its protein half-life has been measured.
Gene: Protein-coding gene on chromosome 8 (53,715,543 to 53,843,558, reverse strand). Ensembl gene ENSG00000047249.
Subcellular location: Cytoplasmic vesicle, clathrin-coated vesicle membrane
Subcellular location (Human Protein Atlas): Actin filaments; Cytosol; Plasma membrane
Pathways (Reactome):
Disease: Blockage of phagosome acidification; Nef Mediated CD4 Down-regulation; Nef Mediated CD8 Down-regulation
Transport of small molecules: Ion channel transport; Transferrin endocytosis and recycling
Cellular responses to stimuli: Amino acids regulate mTORC1
Developmental Biology: Regulation of MITF-M-dependent genes involved in lysosome biogenesis and autophagy
Immune System: ROS and RNS production in phagocytes
Signal Transduction: Insulin receptor recycling
Gene Ontology:
Molecular function: protein binding; ATP hydrolysis activity; enzyme regulator activity; proton-transporting ATPase activity, rotational mechanism
Biological process: endocytosis; endosomal lumen acidification; Golgi lumen acidification; intracellular pH reduction; lysosomal lumen acidification; proton transmembrane transport; regulation of macroautophagy; synaptic vesicle lumen acidification; vacuolar acidification
Cellular component: cytosol; extracellular exosome; lysosomal membrane; membrane; endosome membrane; Golgi membrane; plasma membrane; proton-transporting V-type ATPase complex; vacuolar proton-transporting V-type ATPase, V1 domain; clathrin-coated vesicle membrane; extrinsic component of synaptic vesicle membrane
Genetic constraint (gnomAD): Loss-of-function variants: 27 observed, 45.46 expected, observed/expected ratio (o/e) 0.59, 90% interval 0.44 to 0.82. The upper end of that interval is the gene's LOEUF score, 0.82, which puts it in group 3 of 6, group 1 being the genes least tolerant of losing a copy. Missense variants: 352 observed, 444.44 expected, observed/expected ratio (o/e) 0.79, 90% interval 0.73 to 0.87. Synonymous variants: 146 observed, 155.53 expected, observed/expected ratio (o/e) 0.94, 90% interval 0.82 to 1.08.
Homologues: Orthologues: chimpanzee ATP6V1H (100% identical), macaque ATP6V1H (99% identical), rabbit ATP6V1H (99% identical), guinea pig ATP6V1H (99% identical), pig ATP6V1H (98% identical), rat Atp6v1h (95% identical), mouse Atp6v1h (95% identical), tropical clawed frog atp6v1h (92% identical), dog ATP6V1H (89% identical), zebrafish atp6v1h (87% identical), Drosophila melanogaster VhaSFD (53% identical), Caenorhabditis elegans vha-15 (51% identical), and 1 more.
Diseases named in the same sentence as ATP6V1H in open-access papers:
ATP6V1H is named in the same sentence as 13 diseases in open-access papers, as found by Europe PMC text mining. Sharing a sentence is not in itself a finding about the gene and the disease. The quoted sentences say what the papers report.
osteoporosis (4 papers, 2017 to 2024). A condition of reduced bone mass, with decreased cortical thickness and a decrease in the number and size of the trabeculae of cancellous bone (but normal chemical composition), resulting in increased fracture incidence. "By demonstrating that interventions targeting Atp6v1h can effectively mitigate bone loss, our findings provide important insights into novel therapeutic approaches for osteoporosis." (PMID 38203808, 2024). "Co-segregation between a mutation in the ATP6V1H gene and osteoporosis was reported in a human three-generation pedigree and functional studies performed in zebrafish using CRISPR/Cas9." (PMID 34938269, 2021). "Here we show that happloinsufficiency of ATP6V1H is associated with osteoporosis in both humans and zebrafish." (PMID 28158191, 2017). "Our team was the first to identify ATP6V1H as a causative gene for osteoporosis in 2016." (PMID 38203808, 2024). "Our results indicate that Atp6v1h level influences bone loss in simulated microgravity by modulating the Fos-Jun-Src-Integrin pathway, which, in turn, affects osteoclast activity and bone resorption, with implications for osteoporosis." (PMID 38203808, 2024). "This study elucidates the molecular mechanism of Atp6v1h’s role in osteoporosis and positions it as a potential therapeutic target against environmental bone loss." (PMID 38203808, 2024). "atp6v1h zebrafish mutants showed a reduction in mature bone, reduced bone mass and density, providing functional evidence of ATP6V1H in osteoporosis." (PMID 34938269, 2021). "Furthermore, this study has elucidated the molecular mechanisms by which Atp6v1h contributes to osteoporosis." (PMID 38203808, 2024). "In any event, the bone defect caused by atp6v1h deficiency through activation of mmp9/13 represents a novel finding that offers potential therapeutic entry points for related diseases, since MMP9 levels have been correlated to severity of osteoporosis." (PMID 28158191, 2017).
diabetes (2 papers, 2018 to 2019). "These include genes with known function in islets and diabetes such as ATP6V1H, SOX6, SOCS1 and STX1145–48." (PMID 31123324, 2019). "ATP6V1H gene was mainly studied and discussed about its roles in diabetes in previous researches and the data showed that the down-regulation of its gene expression correlates with the presence of type-2 diabetes." (PMID 29751835, 2018).
neuroblastoma (1 paper, 2025). Neuroblastoma (NB) is the most common solid, extracranial childhood tumor. "Knockdown of ATP6V0D1, but not ATP6V1H, enhanced ellipticine sensitivity, suppressed proliferation and migration, decreased lysosomal uptake, and induced G2/M arrest in neuroblastoma cell lines." (PMID 40552114, 2025).
Paget's disease of the bone (1 paper, 2022). "Tiludronic acid (DB01133), an inhibitor of ATP6V1D, ATP6V1G2, and ATP6V1H, is used for the treatment of Paget's disease of the bone." (PMID 35875800, 2022).
Parkinson disease (1 paper, 2011). A progressive degenerative disorder of the central nervous system characterized by loss of dopamine producing neurons in the substantia nigra and the presence of Lewy bodies in the substantia nigra and locus coeruleus. "Second, and more interesting, the oxidative phosphorylation chain, including seven genes (ATP5C1, ATP6AP1, ATP6V1H, COX5B, COX6B1, NDUFA1, and UQCRC1), five of them shared with Huntington's and Parkinson's disease KEGG categories." (PMID 21541025, 2011).
tuberculosis (1 paper, 2018). A chronic, recurrent infection caused by the bacterium Mycobacterium tuberculosis. "The second network was tuberculosis (P = 1.03E−03), including ATP6V1H, cathelicidin 1 (CATHL1A), CTSS, ITGB2, myeloid differentiation primary response protein MyD88 (MYD88), and RAB5A." (PMID 30514405, 2018).
cancer (6 papers, 2019 to 2025). A tumor composed of atypical neoplastic, often pleomorphic cells that invade other tissues. "249C kills cancer cells by targeting a druggable hotspot within the V-ATPase subunit ATP6V1H and thereby inhibiting biochemical activity, lysosomal acidification, and MP." (PMID 35879364, 2022). "Notably, the upregulation of genes ATP6V1E1 and ATP6V1H associated with V-ATPase subunits facilitates ECM degradation and cancer cell invasion by acidifying the extracellular environment and activating matrix metalloproteinases." (PMID 40165955, 2025). "The reaction rate of ATP-synthase decreased in both cancer cells, and the genes ATP1B3 and ATP6V1H were down-regulated." (PMID 37299011, 2023).
infection (2 papers, 2008 to 2025). The state of being infected such as from the introduction of a foreign agent such as serum, vaccine, antigenic substance or organism. "The ATP6V1H gene, encoding the V1 50/57 kDa subunit, is strongly induced in Mφs upon infection, whereas it is barely expressed in DCs." (PMID 18167562, 2008).
neurodegenerative disease (2 papers, 2018 to 2019). A disorder of the central nervous system characterized by gradual and progressive loss of neural tissue and neurologic function. "Previously published literature has suggested ATP6V1H gene may play a role in the pathogenesis of neurodegenerative diseases after the discovery of SNPs in this gene associated with β-site APP cleaving enzyme in cerebrospinal fluid of Alzheimer’s patient." (PMID 31396262, 2019). "This study identified rs1481950 within ATP6V1H influencing human CSF BACE activity, which indicated that ATP6V1H gene may play some roles in the pathogenesis of neurodegenerative diseases such as AD." (PMID 29751835, 2018).
tumor (2 papers, 2021). "Analyzing the whole-blood expression signature of four growth factor-related genes (ARAF, BRAF, KRAS, and RAF-1) and four genes involved in metabolism (ATP6V1H, OAZ2, PANK2, and PLD3), combined with tumor grade, they were able to predict the efficacy of PRRT with an accuracy of 95%." (PMID 33809226, 2021).
ATP6V1H also shares sentences with these, for which no sentence is quoted: Alzheimer disease (1 paper); osteopetrosis (1); type-2 diabetes (1).